RN7SL515P (RNA, 7SL, cytoplasmic 515, pseudogene)
Gene: Miscellaneous RNA gene on chromosome 13 (41,807,677 to 41,807,973, forward strand). Ensembl gene ENSG00000241406.
Homologues: Orthologues: chimpanzee Metazoa_SRP (99% identical), macaque Metazoa_SRP (88% identical). Paralogues in human: RN7SL1 (78% identical), RN7SL2 (78% identical), RN7SL3 (76% identical), RN7SL45P (76% identical), RN7SL559P (76% identical), RN7SL220P (75% identical), RN7SL543P (75% identical), RN7SL655P (75% identical), RN7SL122P (75% identical), RN7SL20P (75% identical), RN7SL49P (75% identical), RN7SL383P (75% identical), and 703 more.